RN7SL751P (RNA, 7SL, cytoplasmic 751, pseudogene)
Gene: Miscellaneous RNA gene on chromosome 3 (78,938,009 to 78,938,292, reverse strand). Ensembl gene ENSG00000240964.
Homologues: Orthologues: chimpanzee Metazoa_SRP (98% identical), macaque Metazoa_SRP (51% identical). Paralogues in human: RN7SL1 (76% identical), RN7SL2 (76% identical), RN7SL3 (75% identical), RN7SL218P (74% identical), RN7SL788P (74% identical), RN7SL444P (73% identical), RN7SL45P (73% identical), RN7SL543P (73% identical), RN7SL769P (73% identical), RN7SL200P (73% identical), RN7SL220P (73% identical), RN7SL296P (73% identical), and 702 more.